PRMT5 (protein arginine methyltransferase 5)
Diseases named in the same sentence as PRMT5 in open-access papers (continued):
Sharing a sentence is not in itself a finding about the gene and the disease.
tumor (continued). "Therefore, our data suggest that the use of the MTAP inhibitor MTDIA in MTAP+/+ tumors would conserve the noncatalytic tumor-suppressive functions while still accumulating MTA that stimulates additional tumor suppressive functions through PRMT5 inhibition." (PMID 38000655, 2024). "In addition, a previous report did not mention that PRMT5 inhibition can affect the attenuation of the anti-tumor immune system (see Section 5.2)." (PMID 36980950, 2023). "However, PRMT5 knockdown did not affect tumor shrinkage in immunocompromised NOD-SCID gamma (NSG) mice." (PMID 36980950, 2023). "Furthermore, another study revealed that MTAP deletion results in accumulation of the metabolite 2-methylthioadenosine and promotes the synergism between inhibitors of PRMT5 and of type I PRMT (i.e., GSK3368715) in PDAC, a tumor type in which MTAP is frequently deleted." (PMID 35406598, 2022). "Treatment of mantel cell lymphoma (MCL) cell lines with the orally available PRMT5 inhibitor EPZ015666 (GSK3235025) led to inhibition of SmD3 methylation and cell death, while oral administration in MCL xenograft mouse models demonstrated dose-dependent anti-tumor activity." (PMID 35406598, 2022). "Menin can also recruit protein arginine methyltransferase 5 (PRMT5) to the promoter region of Gas1 gene, a key factor of the Hedgehog signaling pathway, and strengthen the inhibition of histone arginine methylation, thereby inhibiting the Hedgehog signaling pathway to achieve the anti-tumor effect." (PMID 36248960, 2022). "Furthermore, PRMT5 depletion blocks tumor metastasis in the liver, lung, and kidney, independent of primary tumor growth." (PMID 35803962, 2022). "Additionally, western blotting showed that knocking down PRMT5 could dramatically upregulate the expression of LKB1 and the p-AMPK in tumor sections, while downregulating the expression of p-mTOR." (PMID 34124017, 2021). "The pharmacological inhibition of PRMT5 by 5′-methylthioadenisine (MTA) or the inhibition of PRMT5 using ShRNA increased RAS-ERK1/2 activity in response to hepatocyte growth factor (HGF) and resulted in tumor suppressive effects by downregulating EGFR and RAF1 signaling in PC12 tumor cells." (PMID 33670008, 2021). "Given the importance of T cells to the tumor microenvironment, we hypothesized that PRMT5 inhibition may have negative immunomodulatory effects on T cells through the PD-L1/PD1 axis." (PMID 35111150, 2021). "Although homozygous deletion of MTAP is associated with increased PRMT5 inhibitor sensitivity in some pancreatic organoids, broader examination of the impact of MTAP status across different tumour cells lines suggests that it is not a reliable biomarker of sensitivity to PRMT5 inhibition." (PMID 34680285, 2021). "To determine whether or not PRMT5 silencing-induced chromatin remodelling would upregulate tumour suppressor pathways, we conducted gene expression, examining canonical pathways linked to upregulated genes." (PMID 33795785, 2021). "However, we still do not understand how PRMT5-mediated H4R3me2s is fully recognized and thereby affects other epigenetic modifications to repress downstream gene expression and promote tumor progression." (PMID 32292506, 2020). "In addition, we did not detect any prominent effect of PRMT5 on proliferating OPCs, and this is in contrast with previous reports of growth arrest consequent to PRMT5 inhibition in tumor cells." (PMID 30026560, 2018).
tumor (continued). "Our results thus demonstrate the importance of PRMT5-mediated arginine methylation for BCSC function and tumor initiation and imply that drug targeting of this pathway could have significant patient benefit by eradicating the cell population responsible for drug resistance and recurrence." (PMID 29262329, 2017). "They used a PRMT5 inhibitor to determine the importance of repressive epigenetic marks in context of EBV tumors and concluded that PRMT5 was critical for B cell transformation and malignancies because the overexpression of PRMT5 helped to silence the tumor suppressor genes." (PMID 28678843, 2017). "However, patient sex, age, degree of tumor differentiation and other parameters had no observable relationship with PRMT5 expression." (PMID 27708221, 2016). "Moreover, PRMT5 overexpression has been shown to promote angiogenesis via activation of the hypoxia-inducible factor 1-alpha (HIF-1α)/VEGF receptor (VEGFR)/protein kinase B (Akt) signaling pathway, emphasizing its role in tumor vascular remodeling and progression." (PMID 40791817, 2025). "This prompted us to hypothesize that the potent antitumor effect of PRMT5 knockdown observed in vivo might not be solely attributable to these direct, cell-intrinsic effects on tumor cells, but likely involves a critical additional component, such as modulation of the tumor immune microenvironment." (PMID 41463372, 2025). "However, our previous study has shown that PRMT5 did not affect tumor growth." (PMID 41463372, 2025). "At present, the PD1/PD-L1 pathway is a hotspot of tumor immunity, and we confirmed by the SRAMP database that the retrieval of PRMT5 and PD-L1 can indeed modify m6A methylation in multiple sites, so we can speculate that METTL3 by methylation modification regulates the expression of PRMT5 and PD-L1." (PMID 34476262, 2021). "While this is the only published study that has shown a lack of MTA accumulation in human tumor tissues, it should be taken into consideration as a possible limitation for targeted therapy involving MTA-cooperative PRMT5 inhibitors." (PMID 41439984, 2025). "Analysis of clinical data and RNA sequencing results from 668 patients from TCGA database revealed that PRMT5 and MAT2A expression was higher in tumor tissues than in normal tissues." (PMID 40450009, 2025). "Immunohistochemical analysis revealed that EP300-AS1 knockdown increased PRMT5 and Ki67-positive cell number without affecting PTBP1 levels, supporting the tumor-suppressive role of EP300-AS1." (PMID 40790019, 2025). "In this study, we revealed a crucial role for PRMT5 in promoting STS cell proliferation by regulating glycolytic flux, suggesting that the effect of PRMT5 on metabolism is not dependent of a specific tumor type." (PMID 37861293, 2023). "To identify the PRMT responsible for arginine methylation of NONO in CRC cells, we examined PRMT1, PRMT3, PRMT4, PRMT5, PRMT6, and PRMT8 mRNA and protein levels in paired tumor and adjacent normal tissues." (PMID 33420374, 2021). "Mechanistically, although PRMT5 does not directly regulate PRC2 enzymatic activity, its methylation of histone H3 interferes with subsequent PRC2-mediated trimethylation, highlighting a complex and tumor-specific interplay between arginine and lysine methylation." (PMID 41204384, 2025).
infection (17 papers, 2016 to 2025). The state of being infected such as from the introduction of a foreign agent such as serum, vaccine, antigenic substance or organism. "The repressive mark H4R3sme2 mediated by PRMT5 significantly decreases upon pathogen infection, which is consistent with previous reports in potatoes." (PMID 40395926, 2025). "Pathogen infection triggers a decrease in PRMT5 protein levels, which in turn reduces the methylation modification of the spliceosome component LSM4, enhancing resistance by optimizing the alternative splicing of immune-related genes." (PMID 40395926, 2025). "To further characterize EPZ015666, we next examined the impact of PRMT5 inhibition on four separate newly immortalized (i.e., less than 9 months post-infection/immortalization) T-cell lines." (PMID 36819050, 2023). "Our data revealed that trVLP infection of PRMT5 or WDR77 knockdown cells was comparable with that of WT cells." (PMID 37276230, 2023). "At the peak of infection (days 9–11), WT and Prmt5+/− mice showed comparable levels of fecal C. rodentium." (PMID 37666668, 2023). "The PRMT5 inhibitor efficiently attenuates ACE2 binding to S1 and dramatically inhibits infection by SARS‐CoV‐2 and its beta, delta, and omicron variants." (PMID 37928266, 2023). "Mice with haploinsufficient levels of Prmt5 showed a diminished capacity to clear the infection and consequently sustained greater tissue injury." (PMID 37666668, 2023). "In MDMs infected with a wild-type strain, knockdown of PRMT5/PRMT7 and low expression of PRMT5 resulted in inefficient virus production like Vpr-deficient strain infections." (PMID 32210193, 2020). "The mean fold-change in PRMT5 was 1 before infection, 1.44 after 3 days, 1.48 after 1 week, 2.6 after 2 weeks, 3.7 after 3 weeks, and 2.3 after 4 weeks." (PMID 32560231, 2020). "The NF462 WT strain showed significantly higher virus titer than the NF462 ΔR strain in cells transfected with siRandom at 12 days post-infection, when the expression levels of PRMT5 and PRMT7 were similar (lanes 1 and 5)." (PMID 32210193, 2020). "We further discovered that both the RNA and protein levels of PRMT5 were downregulated after infection with either a virulent strain of Pst carrying an empty vector (EV) or the avirulent strain Pst (AvrRpt2)." (PMID 30783097, 2019). "Future experimental validation and analysis will help elucidate the regulatory mechanism of PRMT5 upon pathogen infection." (PMID 30783097, 2019). "Although the AGO2 protein accumulated to a higher level after bacterial challenge, less sDMA of AGO2 was detected after infection and this decrease was correlated with the decreased level of PRMT5." (PMID 30783097, 2019). "Cell counts at multiple time points after PRMT5-CRISPR lentiviral construct infection revealed reduced numbers compared to EGFP-CRISPR controls." (PMID 30026560, 2018). "Interestingly, the expression pattern of PRMT5 in the transcriptomic data shows a consistent decline trend over time with the level of H4R3sme2 after pathogen infection." (PMID 40395926, 2025). "Besides, gene-specific knockdown of Prmt5 in mouse peritoneal macrophages alleviated Mtb-mediated repression of ITCH during infection." (PMID 35658060, 2022). "We speculate that reduced PRMT5 expression during infection may lead to reduced arginine methylation of AGO2, resulting in accumulation of both AGO2 and, via reduced interaction with TSNs, accumulation of AGO2-associated sRNAs, to promote plant immunity." (PMID 30783097, 2019). "Finally, we found that PRMT5 upregulation starts as early as two weeks post-infection." (PMID 32560231, 2020). "Using a co-culture model of infection and immortalization, we found that EPZ015666 is capable of blocking HTLV-1-mediated T-cell immortalization in vitro, indicating that PRMT5 enzymatic activity is essential for the HTLV-1 T-cell transformation process." (PMID 36819050, 2023).
infection (continued). "Using a co-culture model of infection and immortalization, we found that EPZ015666 is capable of blocking HTLV-1-mediated T-cell immortalization in vitro, indicating that PRMT5 enzymatic activity is essential during transformation of HTLV-1-infected T-cells." (PMID 36819050, 2023). "To determine if PRMT5 is required for efficient T-cell transformation, we performed an in vitro co-culture infection and immortalization assay in the presence and absence of EPZ015666." (PMID 36819050, 2023). "By 15–17 d post-infection, 31% of the WT mice had no detectable fecal C. rodentium compared with 8% among the Prmt5+/− mice." (PMID 37666668, 2023). "Consequently, siRNA-mediated depletion of YY1 or PRMT5 rescued ITCH expression, thereby compromising the levels of Mtb-induced ADRP and CD36 and limiting FM formation during infection." (PMID 35658060, 2022). "Immunostaining of viral ORF2 antigen by 2G8 antibody suggested that Kernow C1/p6 infection was enhanced upon PRMT5 or WDR77 knockdown, which was also supported by the flow cytometry data as evidenced by increased HEV infection (ORF2 positive cells) upon PRMT5 and WDR77 knockdown." (PMID 37276230, 2023). "However, it remains unclear whether PRMT5 acts as a host cell factor that is important in BLV gene expression and infection." (PMID 32560231, 2020). "Evidence in support of the role played by PRMT5 in cellular transformation comes from the experiments carried out by Alinari and colleagues, in which the authors showed that upon EBV infection of normal B lymphocytes, PRMT5 protein levels increase as early as 4 to 8 days post-infection." (PMID 30613353, 2018). "Furthermore, our results showed that HBV de novo infection (or transfected with HBV-expressing pCH-9/3091 plasmid) obviously reduced the levels of Rme2sy and H4R3me2s in HepG2-NTCP and HepG2 cells, suggesting that HBV replication attenuates the methylase activity of PRMT5 in vitro." (PMID 34373747, 2021). "HEK293T cells were transiently transfected with Flag-PRMT5 and Flag-WDR77 with or without infection by Sendai virus (SeV)." (PMID 37563140, 2023). "However, the function of PRMT5 in regulating AGO proteins and RNAi, especially in host immune responses against pathogen infections, has not been previously reported in any system." (PMID 30783097, 2019).
hematological malignancies (10 papers, 2019 to 2026). "Noteworthy, for some of these epigenetic effectors, such as NSD2 and PRMT5, there are small molecule inhibitors currently being tested in clinical trials for solid and hematological malignancies." (PMID 40504449, 2025). "Clinical inhibition of PRMT activity has gained significant interest in the treatment of adult solid cancers and haematological disease with PRMT5 inhibitors rapidly entering phase I/II clinical trials." (PMID 40823091, 2025). "PRMT5, a type II protein arginine methyltransferase, is highly expressed in various solid tumors and hematologic malignancies." (PMID 39614393, 2024). "The precise roles of PRMT5 are well known both in hematopoiesis and in several hematological malignancies." (PMID 36358861, 2022). "There are currently six clinical trials involving Type I and PRMT5 inhibitors in hematological malignancies." (PMID 36358861, 2022). "PRMT5 is the most-expressed PRMT in a large set of cell types and human tissues, and the various roles of PRMT5 are well characterized either in normal hematopoiesis or in hematological malignancies." (PMID 36358861, 2022). "Protein arginine methyltransferase 5 (PRMT5), an enzyme that catalyzes the symmetric di-methylation of arginine residues, is frequently overexpressed and dysregulated in both human solid and hematologic malignancies." (PMID 33989303, 2021). "Growing evidence suggests that PRMT5 expression and activity are dysregulated in various solid and hematological malignancies." (PMID 31694585, 2019). "Moreover, the inhibitor targeting PRMT5 has already entered Phase II clinical trials for treating with relapsed/refractory hematologic malignancies, demonstrating its therapeutic potential." (PMID 41513606, 2026). "Inhibitors directed against PRMTs type I, i.e., PRMT1, CARM1, PRMT5, and PRMT7, have been tested on hematological malignancy models and have shown a significant decrease in malignant cell proliferation and an increased apoptosis." (PMID 36358861, 2022).
cardiovascular diseases (5 papers, 2018 to 2021). "However, reports published recently suggest that differential PRMT5 levels may serve as a risk indicator for developing certain cardiovascular diseases or may reduce/promote its related morbidities." (PMID 34685445, 2021). "Collectively, these discussed studies suggest that the role of PRMT5 is context-dependent, and therefore, the elucidation of the PRMT5 molecular activity in contribution to different cardiovascular diseases is an area worthy of further exploration." (PMID 34685445, 2021). "This opens up a wide range of therapeutic applications for PRMT5 inhibitors in other diseases such as cardiovascular disease, and perhaps neurodegenerative disorders, etc." (PMID 34685445, 2021). "In contrast, increased PRMT5 expression may enhance the pathological progression of inflammatory-driven cardiovascular diseases." (PMID 34685445, 2021). "The number of studies investigating the role of PRMT5 in cardiovascular diseases is limited." (PMID 34685445, 2021). "Furthermore, the dysregulation and upregulation of PRMT5 in several cardiovascular disorders and neurological disorders raise the question of how PRMT5 may be therapeutically targeted for disease treatment." (PMID 34685445, 2021). "However, no research has investigated the correlation between PRMT5 and cardiovascular diseases." (PMID 30704408, 2019).
prostate (4 papers, 2012 to 2023). "Taken together, the results from this study provide insight into the functional roles of PRMT5 in the control of cell growth and in prostate tumorigenesis." (PMID 22952863, 2012). "Therefore, the PRMT5 function is regulated by its subcellular localization, and this nucleocytoplasmic transport may play an important role in prostate tumorigenesis." (PMID 22952863, 2012).
adenocarcinoma (3 papers, 2013 to 2026). A common cancer characterized by the presence of malignant glandular cells. "To further analyse the induction of PRMT5 expression by STAT3 in NSCLC cells, we generated STAT3-knockout (STAT3-KO) cells by using the CRISPR/Cas9 system in A549 (EGFR wild type, adenocarcinoma) and HCC827 cells (EGFR mutant, adenocarcinoma)." (PMID 38760429, 2024).
hematological cancers (3 papers, 2021 to 2025). "Consequently, PRMT5 has emerged as a critical therapeutic target in numerous malignancies, with small molecule inhibitors designed to reduce PRMT5 activity currently undergoing clinical trials, particularly in solid tumors and hematological cancers characterized by MTAP deletion." (PMID 39678513, 2024). "Protein arginine methyltransferase 5 (PRMT5) is a type II protein arginine methyltransferase (PRMT) enzyme that is frequently dysregulated in both solid and hematologic cancers." (PMID 33989303, 2021).
bacterial infection (2 papers, 2019 to 2020). "Conversely, among the ten AGOs in Arabidopsis, only AGO2 is induced by bacterial infection and AGO2 positively regulates immunity by protein arginine methyltransferase 5 (PRMT5)-mediated dual regulation of this protein as well as associated sRNA levels to ensure appropriate plant immune responses." (PMID 32764599, 2020).
head and neck tumors (2 papers, 2024). "And we also found that the expression of PRMT5 in head and neck tumors was significantly correlated with immune cell infiltration, m6A as well as the expression of ferroptosis-related genes, and drug sensitivity." (PMID 38663941, 2024). "Here, we found that PRMT family members are significantly overexpressed in head and neck tumors and that PRMT5 may serve as an independent prognostic factor in head and neck tumors." (PMID 38663941, 2024). "Head and neck tumors have limited survival and poor outcomes due to the overexpression of FXR1 and PRMT5." (PMID 38709899, 2024).
heart disease (2 papers, 2022 to 2025). "Collectively, our findings offer new insights into the molecular mechanisms underlying cardiac function and suggest that PRMT5 is a potential therapeutic target for heart diseases." (PMID 40076920, 2025). "Given the critical role of adrenergic signaling in heart rate and contractility, our findings provide novel insights into cardiac molecular mechanisms and suggest that PRMT5 is a promising therapeutic target for heart disease." (PMID 40076920, 2025). "Protein arginine methyltransferase 5 (PRMT5), a key enzyme involved in gene expression, signal transduction, and RNA processing, has been revealed to be an important factor in heart disease." (PMID 40076920, 2025).